ATAD1 (ATPase family AAA domain containing 1)
Diseases named in the same sentence as ATAD1 in open-access papers (continued):
Sharing a sentence is not in itself a finding about the gene and the disease.
cancer (11 papers, 1999 to 2024). A tumor composed of atypical neoplastic, often pleomorphic cells that invade other tissues. "The mutational landscape of ATAD1 in cancer samples of 10953 patients was analyzed on cBioPortal web server." (PMID 36362897, 2022). "We next sought to pharmacologically exploit ATAD1 deficiency in relevant cancer models, drawing on our discovery of synthetic lethality with MARCH5." (PMID 36409067, 2022). "ATAD1 is co-deleted with PTEN in cancer and its loss confers synthetic lethal vulnerabilities." (PMID 36409067, 2022). "That ATAD1 loss sensitizes to proteasome dysfunction could have therapeutic implications for hundreds of thousands of cancer patients with Del(10q23) tumors, especially considering that drugs targeting the proteasome are already approved for the treatment of cancer." (PMID 36409067, 2022). "Sustained proliferation is the most important characteristic of cancer cells, so the influence of ATAD1 and ACBD5 downregulation on A172 or U251 cell proliferation was assessed using a CCK8 assay." (PMID 38406287, 2024). "PRAD showed the highest ATAD1 alteration frequency compared to other cancer types, in which deep deletion occupied the majority." (PMID 36362897, 2022). "The effect of ATAD1 on apoptosis likely extends beyond PTEN-null cancers into a broader physiological context." (PMID 36409067, 2022). "Overall, this work demonstrates that cancer cells which have lost ATAD1 become more vulnerable to disruptions in the protein removal pathway mediated by MARCH5, including via already existing drugs." (PMID 36409067, 2022). "In this work we describe how the collateral deletion of ATAD1, a mitochondrial protein extractase, sensitizes cancer cells to apoptosis induced by proteasome dysfunction." (PMID 36409067, 2022). "Here, we describe how the loss of ATAD1, which is adjacent to and frequently co-deleted with PTEN, predisposes cancer cells to apoptosis triggered by proteasome dysfunction and correlates with improved survival in cancer patients." (PMID 36409067, 2022). "For example, the loss of the tumor suppressor gene PTEN, the second most deleted gene in cancer, frequently involves the removal of the nearby ATAD1 gene." (PMID 36409067, 2022). "Next, we examined the significance of ATAD1 across different cancers." (PMID 36362897, 2022). "If confirmed by further translational work, these findings could have important clinical impact given how frequently PTEN and ATAD1 are lost together in cancer." (PMID 36409067, 2022). "We found that the generalization value of ATAD1 could be applied to other cancers such as KIRC and UCEC." (PMID 36362897, 2022). "(C) Frequency of ATAD1 deep deletions across various cancer types; data from cBioPortal." (PMID 36409067, 2022). "In a previous report, miR-140 was shown to be sponged by circ-ATAD1 during cancer progression." (PMID 34479600, 2021). "Based on our knowledge, the role of circ-ATAD1 in other cancers is unknown." (PMID 35505304, 2022). "Based on our knowledge, the function of circ-ATAD1 in other cancers is unknown." (PMID 34857012, 2021). "Analysis of genomic data from The Cancer Genome Atlas corroborated these protein-level findings, as the majority of tumors harboring deep deletions in PTEN also had deep deletions in ATAD1." (PMID 36409067, 2022). "First, we inspected gene aberrations of the PAPSS2, ATAD1, KLLN, and PTEN loci in 26 cancer types." (PMID 37984988, 2024). "Experiments revealed that without ATAD1, cancer cells started to rely more heavily on an alternative mechanism to remove harmful proteins: the process centers on MARCH5, an enzyme which tags molecules that require removal so the cell can recycle them." (PMID 36409067, 2022). "To verify whether ATAD1 has a broad value, we investigated differential expression and examined DFS across cancers." (PMID 36362897, 2022).
cancer (continued). "Our preliminary microarray analysis has revealed an altered circ-ATAD1 expression in CRC as well as an inverse correlation between circ-ATAD1 and miR-618 (data not shown), a crucial player in cancer biology." (PMID 35505304, 2022). "In contexts unrelated to cancer, it has been shown that the absence of ATAD1 leads to the accumulation of TA proteins on the OMM and significant mitochondrial dysfunction." (PMID 36409067, 2022).
degenerative diseases (2 papers, 2021 to 2024). "To date, ATAD1 has not been directly linked to the onset of neurodegenerative diseases." (PMID 39795902, 2024).
ATAD1 also shares sentences with these, for which no sentence is quoted: malaria (386 papers); infection (200); parasitemia (31); falciparum malaria (13); frontotemporal dementia (12); amyotrophic lateral sclerosis (9); co-infection (6); anaemia (4); Paget’s disease of bone (4); autosomal dominant disease (2); bladder cancer (2); cerebral malaria (2); cholera (2); hereditary spastic paraplegia (2); hyperekplexia (2); myopathies (2); neurodevelopmental disorder (2); Paget disease (2); Schistosoma haematobium infection (2); thalassaemia (2); vivax malaria (2); abscesses (1); AIDS (1); Alpha-thalassemia (1); Alzheimer disease (1); anaplasmosis (1); bipolar disorder (1); cardiac hypertrophy (1); colitis (1); dementia (1).
A further 33 diseases each share a sentence with ATAD1 in 1 paper.